PLK4 (polo like kinase 4)
Diseases named in the same sentence as PLK4 in open-access papers (continued):
Sharing a sentence is not in itself a finding about the gene and the disease.
tumor (continued). "A more modest increase in Plk4 expression and centrosome number facilitated spontaneous tumour formation in mice and recapitulated features of chromosomal instability in human tumours." (PMID 35164835, 2022). "Increasing evidence indicates that PLK4 is aberrantly expressed in patient‐derived tumor samples, including colorectal cancer, breast cancer, bladder cancer, and melanoma, but is also expressed at low levels in proliferative tissues." (PMID 35670224, 2022). "PLK4 expression contributes to the activation of metabolic and immune signaling pathways in various tumor types according to GO and KEGG pathway enrichment analyses." (PMID 36620611, 2022). "And in intracranial tumor mouse models, PLK4 inhibition increased tumor-infiltrating M1 macrophages." (PMID 36620611, 2022). "Because of the key roles in tumor growth and development, PLK4 is considered to be one of the most potential tumor therapeutic targets." (PMID 34342940, 2021). "Polo‐like kinase 4 (PLK4) has been reported to contribute to tumor growth, invasion, and metastasis." (PMID 34342940, 2021). "The results indicated that tumor tissues of the shPLK4‐2 group contained lower PLK4 expression than those of the shNC group." (PMID 34342940, 2021). "The retrospectively analyzed data from 560 surgical NSCLC patients showed that the high level of Plk4 was found to be correlated with larger tumor size, wider lymphatic metastasis and higher TNM stage." (PMID 33777739, 2021). "High levels of PLK4 correlate with tumor growth, aggressive progression and treatment resistance representing a poor-prognostic marker." (PMID 34065956, 2021). "In summary, our findings reveal the molecular mechanism of talazoparib‐induced anti‐tumor effect, and suggest a potential clinical use of talazoparib‐targeted lncRNA PLK4/YAP‐dependent cellular senescence for the treatment of HCC." (PMID 32243714, 2020). "Despite this, depletion of FAM46C enhanced tumor progression, suggesting that the dominant effect was to liberate Plk4 kinase activity." (PMID 32807875, 2020). "Overall, the Plk1 and Plk4 expression was clearly higher in tumor cells than in PBMCs from healthy donors compared to the other members of the Plk family." (PMID 32060361, 2020). "In our study, lncRNA microarray indicated that lncRNA PLK4 is significantly down‐regulated in HCC patient tumour tissues." (PMID 32243714, 2020). "In this study, we established a cell model of PLK4 knockdown and overexpression in LN‐18, A172 and LN‐229 cells and found that knockdown of PLK4 expression enhanced the anti‐tumour effect of bortezomib." (PMID 32126150, 2020). "Real‐time PCR showed that the lncRNA PLK4 expression was markedly down‐regulated in the liver tumour tissues, compared with the adjacent tumour tissues.Consistently, the expression of lncRNA PLK4 was also significantly reduced in HCC cell lines." (PMID 32243714, 2020). "Local hypoxia in tumors increases VEGF-A signaling, leading to high CyclinE/cdk2 that promotes EC centrosome overduplication, and elevated Plk4 expression occurs in human and mouse tumor vessels." (PMID 32699963, 2020). "Overexpression of polo‐like kinase 4 (PLK4) is commonly reported in tumour cells and increases their invasive and metastatic abilities." (PMID 32126150, 2020). "And we found that rs3811741 presented cis‐eQTL with PLK4 in HCC tumor tissues after adjustment for the CpG methylation level and copy number alterations." (PMID 31489978, 2019). "And as drawn in the growth curve, it illustrated that PLK4 promoted tumorigenesis through increasing tumor weight and volume in vivo, which was consistent with the previous consequences in vitro." (PMID 29352113, 2018).
tumor (continued). "The results showed that the expression level of Akt was stable among primary tumor tissues with diverse expression level of PLK4, whereas expression level of p-Akt in tissues of NB liver metastasis was higher than that of primary tumors." (PMID 29352113, 2018). "Knockdown PLK-4 significantly inhibited cell proliferation, invasion and promoted cell apoptosis in vitro whereas decreased tumor growth in vivo." (PMID 30315225, 2018). "The recent observation that transgenic mice with high Plk4 levels are tumor prone provides compelling evidence for the idea that centrosome amplification can lead to neoplastic transformation." (PMID 30035751, 2018). "Mutant mice that are subject to centrosome amplification due to Plk4 overexpression are also tumor prone, providing broader support for the notion that supernumerary centrosomes are causally implicated in neoplastic transformation." (PMID 30035751, 2018). "Recently, Tian and colleagues reported PLK4 overexpression in peripheral NB tumor samples and primary NB cell lines." (PMID 30400339, 2018). "PLK-4 silencing inhibited cell proliferation, metastasis and tumor growth in vitro and in vivo, and promoted apoptosis." (PMID 30315225, 2018). "The miR-126/PLK-4 axis inhibits tumor tumorigenesis and progression mainly through regulating proliferation and cell cycle." (PMID 30315225, 2018). "There appears to be very little intrinsic resistance to PLK4 inhibition based on the effects on tumor cell proliferation and tumor weight observed in this study." (PMID 27902970, 2017). "The transgenic mouse we have generated allows us to induce centriole duplication in response to elevated Plk4 and so begin to address the relationship between multiple centrosomes and tumour formation." (PMID 26701933, 2015). "In this study, we disrupted the KLF14 gene in mice and report that KLF14 serves as a novel tumour suppressor essential for limiting Plk4-directed centrosome amplification." (PMID 26439168, 2015). "Correlational analysis revealed a significant negative correlation between the protein expression levels of KLF14 and Plk4 in both breast and colon tumour tissues (Spearman's ρ=−0.6 and −0.8, respectively)." (PMID 26439168, 2015). "The mitotic figures in these Plk4 over-expressing tumour cells were typically bipolar with multiple centrosomes at the poles (71%)." (PMID 26701933, 2015). "Since PLK4 expression was significantly corrected to AFP, tumor size and clinical stage, we further determined the relationship between PLK4 expression and the survival of patients subclassified as ‘large tumor’, ‘AFP (≥20 ng/ml)’ and ‘Stage (III–VI)’." (PMID 22829937, 2012). "Decreased PLK4 expression in HCC is significantly related to tumor size, serum AFP, and clinical stage." (PMID 22829937, 2012). "On the other hand, recent studies provided a comprehensive understanding of PLK4’s role in tumor progression and cell differentiation." (PMID 22829937, 2012). "In the case of Plk4, over 50% of aged Plk4 heterozygous (Plk4+/-) mice develop tumours in comparison to only 3% of their wild-type littermates, the major site of tumour formation being the liver and lung." (PMID 21324136, 2011). "Similarly as our previous studies, E-cadherin and N-cadherin expression in tumor tissues varied with PLK4 levels and correlated with the degree of differentiation." (PMID 40860200, 2025). "PLK4 was found to be overexpressed in aggressive TNBC compared with non-TNBC patient samples associating with centrosome amplification, which strongly correlates with tumor aggressiveness and metastases." (PMID 41092110, 2025). "From a unified perspective, PLK4 may drive tumor progression in skin through mechanisms involving metastasis, enhanced cell cycle activity, and disruption of tumor suppressor signaling." (PMID 40940791, 2025).
tumor (continued). "Epas1 might also promote infiltration of tumor-specific T cells into tumors, like Hif1a, since Epas1 controls expression of genes involved in tumor infiltration of immune cells, such as Plk4 and Tstd2." (PMID 39925817, 2025). "Some other authors also acknowledge that PLK4 also facilitates the invasiveness and metastasis of tumor cells via an activation of the ARP2/3 complex (ARP—actin-related protein) and small GTPases RHO and RAC despite its a well-documented role in the cell cycle." (PMID 39329988, 2024). "However, in the context of Plk4 overexpression, during repeated DNA damage–driven blood cell attrition, loss of RAIDD expression and hence PIDDosome function cancelled out the Plk4-induced delay in tumor latency." (PMID 38552015, 2024). "Tumor PLK4 protein was mainly expressed in the cytoplasm or membrane." (PMID 38326803, 2024). "Tumor latency was again significantly delayed in mice carrying the Plk4 transgene." (PMID 38552015, 2024). "Tumor latency was comparable between EμMYC and EμMYC/Plk4 mice." (PMID 38552015, 2024). "Therefore, elevated tumor PLK4 protein expression is related to lymphovascular invasion in EC patients who underwent surgical resection." (PMID 38326803, 2024). "However, studies on tumor formation in mice by overexpression of PLK4, the principal kinase regulating centrosome duplication, led to ambiguous results, as some but not all models resulted in increased tumorigenesis." (PMID 39466849, 2024). "Patients with a tumor PLK4 IHC score > 6 had worse OS than those with a score ≤ 6 (P = 0.006)." (PMID 38326803, 2024). "Moreover, ex vivo cultured tumor cells established from these animals were still proficient in expressing the Plk4 transgene upon doxycycline addition." (PMID 38552015, 2024). "Therefore, our findings demonstrate that Plk4 overexpression influences the communication between cells and the tumor microenvironment, impacting malignancy in different ways." (PMID 36797240, 2023). "However, investigations into the correlation between PLK4 expression and tumor growth and prognosis in LUAD are limited." (PMID 37760631, 2023). "Moreover, Plk4 deregulation promotes tumor growth and metastasis in mouse models and is significantly associated with poor patient prognosis." (PMID 36797240, 2023). "Besides, another study illuminates that PLK4 inhibits the apoptosis of tumor cell by stimulating phosphatidylinositol 3-kinase/protein kinase B (PI3K/Akt) signaling pathway in neuroblastoma cell lines." (PMID 37351847, 2023). "To determine whether there is a relationship between the expression levels of PLK4 and the tumor immune microenvironment (TIM), we explored the relationship further." (PMID 36620611, 2022). "Moreover, WB assay also showed that PLK4 expression was higher in tumor tissues injected with bufalin-treated cells compared to those inoculated with control cells." (PMID 35912011, 2022). "However, the expression of PLK4 compared to paracancerous tissue in different tumor types is different." (PMID 36176741, 2022). "However, the studies in mice with high expression of PLK4 provided contradictory results on the contribution of centrosome amplification to tumor progression." (PMID 35365182, 2022). "Although roles of PLK4 in solid cancers have been studied, there was a controversy in whether PLK4 as an oncogene or tumor suppressor." (PMID 36051696, 2022). "In conclusion, our study suggests that PLK4 may be a potential biomarker for aberrant tumor proliferation and immune infiltration and prognostic relevance in ccRCC and may also be a new immune-related therapeutic target." (PMID 36176741, 2022).
tumor (continued). "We then further explored the functions of PLK4 in vivo using the 5637 tumor xenografts assay." (PMID 34342940, 2021). "In summary, these results indicated that the inhibition of PLK4 expression could suppress the growth of BC tumor in vivo." (PMID 34342940, 2021). "In addition, the anti-tumor effect of bortezomib was enhanced after Plk4 knockdown in three (LN-18, A172 and LN-229) GBM cell lines and xenograft experiments." (PMID 33777739, 2021). "Next, we also confirmed the effect of PLK4 knockdown on BC tumor growth in vivo." (PMID 34342940, 2021). "Furthermore, molecular analyses indicated SNHG16 deletion inhibited the expression of SNHG16 and PLK4, but promoted the level of miR-338-3p in excised tumor masses compared with the sh-NC group." (PMID 32536824, 2020). "Similarly to Plk1, Plk4 was recently found to be aberrantly expressed and involved in tumor progression." (PMID 32060361, 2020). "Moreover, the PLK4 mRNA expression was aberrantly activated in HCC tumor tissues compared with adjacent tissues both in paired and unpaired tissues in TCGA database (P < .001)." (PMID 31489978, 2019). "Additionally, in vivo experiments, after injection with sh-PLK-4 and MOCK into the nude BALB/c male mice respectively, the growth rate and tumor weight were markedly less after PLK-4 knockdown." (PMID 30315225, 2018). "In addition, IHC analysis revealed that the tumor tissues of the miR-126 overexpression group displayed much weaker staining of PLK-4, Ki-67." (PMID 30315225, 2018). "The study showed the expression level of PLK4 in NB tissues was remarkably upregulated and high expression of PLK4 was negatively correlated with clinical features and survival, which suggested that PLK4 could be a potential tumor-promoting factor of NB." (PMID 29352113, 2018). "Inhibition of PLK4 triggers failure of centriole duplication, while PLK4 overexpression promotes centriole overduplication which results in the formation of extra centrosomes with subsequent genome instability and propensity for tumor formation." (PMID 29340047, 2017). "Indeed, the spontaneous tumours from KLF14-KO mice displayed high levels of Plk4 expression and centrosome amplification compared with WT mouse tissues." (PMID 26439168, 2015). "In the present study, we found low expression of PLK4 in HCC was significantly associated with other malignant tumor characteristics, such as advanced stage and high serum AFP, indicating that PLK4 might be served as a hallmark of advanced stage tumors." (PMID 22829937, 2012). "Collectively, downregulation of PLK4 in tumor tissues may facilitate tumor progression, subsequently leading to poor prognosis." (PMID 22829937, 2012). "Interestingly aged Plk4 heterozygous mice display haploinsufficiency with tumours developing at a high frequency in major sites such as the liver and lung." (PMID 19607708, 2009). "Finally, it has been proposed that the small increases in centrosome number induced by a low-to-moderate level of PLK4 are permissive for tumor development, whereas high levels of PLK4 trigger larger number of centrosomes and are likely to be harmful for long-term cell survival." (PMID 35365182, 2022). "In addition, inhibition of PLK4 in genomic or pharmacologic could suppress tumor growth or increase sensitivity to radiation and chemotherapy." (PMID 34342940, 2021). "The relationship between Plk4 and tumor-associated inflammation has not been widely studied." (PMID 33777739, 2021).
tumor (continued). "In addition, polo‐like kinase 4‐associated lncRNA (PLK4) is a downregulated lncRNA in HCC tissues and cell lines, and may serve as a tumour suppressor featured with YAP inactivation and subsequent cellular senescence induction." (PMID 32779318, 2020). "Moreover, we established that polyploidy induced by PLK4 inhibition increased tumor cell susceptibility to DNA-damaging agents while sparing non-tumor cells." (PMID 30400339, 2018). "In parallel, RP‐1664, a novel PLK4 inhibitor, disrupts centriole biogenesis and is effective in TRIM37‐amplified tumours." (PMID 41537447, 2026). "Treatment of PDXs with a PLK4 inhibitor CFI-400945, reduced tumor growth, proliferation markers, and tumor-initiating cells." (PMID 41488365, 2025). "We assessed PLK4, PHOX2B, CXCR4, and cyclin D1 expression by IHC in tumor tissues from the same patients exhibiting variable differentiation status." (PMID 40860200, 2025). "Another study showed that PLK4 induced the activation of IKBKE/NF-κB, which resulted in augmented tumor growth and chemoresistance in a mouse model." (PMID 41488365, 2025). "The interaction between FAM46C and Plk4 suggests that the regulation of centrosome duplication and consequently cell cycle by FAM46C contributes to their tumor-suppressive roles." (PMID 37018411, 2023). "To validate the expression of PLK4, we collected 15 CRC patient-matched fresh tumor and adjacent non-tumor tissue." (PMID 37324947, 2023). "Based on these results, PLK4 seems to inhibit the infiltration of immune cells into TME, allowing tumor cells to evade the immune system." (PMID 36620611, 2022). "Based on the Sangerbox and TISIDB databases, we examined the relationship between PLK4 expression and TIIC levels in various tumor types." (PMID 36620611, 2022). "The PLK4 inhibitor CFI400945 was administered to mice, followed imaging and HE staining showed that CFI400945 can significantly inhibit tumor progression." (PMID 36620611, 2022). "For example, the regulation of polo-like kinase 4 (Plk4) levels through CUL1 activity, which inhibits the biogenesis of excessive daughter centrioles, exerts tumor suppressor function in cells." (PMID 34299191, 2021). "MAD2L1, NCAPG, PBK, and PLK4) was validated using qRT-PCR in MDA-MB-231 and BT-549.Taken together, our data highlighted activation of several tumor suppressor transcriptional regulatory networks in response to DNMT inhibition leading to tumor cell death." (PMID 34565361, 2021). "The upregulated Plk4 subsequently activated the ATR/CHEK1 pathway which is critical for maintaining genomic stability and promoting tumor progression." (PMID 33777739, 2021). "It is not clear whether changes in Plk4 levels are the cause of tumor development or progression." (PMID 33777739, 2021). "Significant correlations were found between PLK4 expression and three parameters including clinical stage (P = 0.034), serum AFP positive (P = 0.019) and tumor size (P = 0.032)." (PMID 22829937, 2012). "HCC patients with low PLK4 expression had a higher tendency to be with advanced stage, high level of serum AFP and large-size tumor." (PMID 22829937, 2012). "Stratified survival analysis of HCC, according to clinical stage, tumor size and serum AFP, evaluated PLK4 expression to be closely correlated with survival of HCC patients with stage III–IV, larger tumor size and high-level AFP." (PMID 22829937, 2012). "Disease-free survival (DFS) was not different between patients with tumor PLK4 IHC scores > 0 and ≤ 0 (P = 0.154) but was reduced in patients with scores > 3 vs. ≤ 3 (P = 0.009) and > 6 vs. ≤ 6 (P < 0.001)." (PMID 38326803, 2024). "In addition, PLK4 facilitates centrosome duplication, accelerates cytoskeletal rearrangement and EMT, and contributes to tumor cell proliferation, invasion, and metastasis." (PMID 38326803, 2024). "In EC patients who underwent surgical resection, DFS did not vary between patients with tumor PLK4 IHC scores > 0 and ≤ 0 (P = 0.154)." (PMID 38326803, 2024).